APOL1 (apolipoprotein L1)
Diseases named in the same sentence as APOL1 in open-access papers (continued):
Sharing a sentence is not in itself a finding about the gene and the disease.
renal cell carcinoma (8 papers, 2014 to 2025). "Although the relative risk of renal cell carcinoma associated with chronic kidney injury is particularly high among sub-Saharan African ancestry populations, it is unclear yet whether the APOL1 gene risk variants (RV) for kidney disease additionally elevate this risk." (PMID 35159001, 2022). "In the current study, we utilize renal cell carcinoma (RCC) cells as a research model in which intrinsic high expression levels of APOL1 GO protein are tolerated and compatible with robust cell proliferation." (PMID 35159001, 2022). "APOL1 has protective effect on normal renal cells, Inhibiting the expression of APOL1 can promote the progression of renal cell carcinoma." (PMID 34087900, 2021). "Similarly, APOL1 protects renal cells from renal cell carcinoma." (PMID 33435917, 2021). "However, it is not known whether the APOL1 risk variants for CDK elevate the risk of renal cell carcinoma in these populations." (PMID 35159001, 2022). "Furthermore, APOL1 expression may be protective against renal cell carcinoma." (PMID 25294808, 2014).
bladder cancer (7 papers, 2019 to 2024). "Among them, the levels of APOL1 in the bladder cancer, cystitis and upper urinary tract cancer samples were higher than those in the healthy control samples." (PMID 38410113, 2024). "At present, research on the relationship between APOL1 and bladder cancer mainly uses the TCGA database to conduct bioinformatics analysis for prognostic evaluation and autophagy-related functions." (PMID 38410113, 2024). "In our study, the content of APOL1 in the bladder cancer, cystitis and upper urinary tract cancer samples was higher than that in the healthy control samples, suggesting that the protein is highly expressed in the urine of patients with urinary diseases." (PMID 38410113, 2024). "When tested as individual gene, 9 genes from the 11-ARG signature (APOL1, ATG4B, CASP3, ITGA3, P4HB, PRKCD, ULK2, and WDR45) exhibited a significant association between mRNA expression levels and overall survival of bladder cancer patients." (PMID 33925460, 2021). "Combined with the relationship between APOL1 and other malignancies, we speculated that APOL1 may affect proliferation, invasion and autophagy in bladder cancer, thus affecting prognosis." (PMID 38410113, 2024). "APOL1 genetic variants are reported to be a major drive of kidney diseases, but their function in bladder cancer has not been reported." (PMID 33925460, 2021). "While higher expression of APOL1, ATG4B, ITGA3, WDR45, CASP3, and PRKCD is associated with favorable survival in human bladder cancer patients, increased ULK2 and P4HB mRNA levels are negatively correlated to overall survival of bladder cancer patients." (PMID 33925460, 2021). "Urine IL-8, Ficolin-3, Apolipoprotein L1, Properdin, and Proteinase 3 also need to be validated both independently and as a multi-marker panel in future cross-sectional and longitudinal cohorts to confirm if they are good indicators for bladder cancer disease progression." (PMID 37016361, 2023). "Among these five genes (GPC2, SETBP1, FGF11, APOL1, H1–2) related to the prognosis of patients with BC, there are no reports or experiments about these genes related to bladder cancer, except for H1–2." (PMID 34315402, 2021).
Stroke (7 papers, 2015 to 2023). Sudden impairment of blood flow to a part of the brain due to occlusion or rupture of an artery to the brain. "In another study, low levels of SERPINA1, PLG, KLKB1, ITIH4, and APOL1 in serum of patients with lacunar stroke were associated with poor prognosis and increased risk of recurrent stroke or myocardial infarction and cognitive decline." (PMID 31242583, 2019). "The SIREN investigators involved in the largest study on stroke in Africa to date, were the first to demonstrate an association between APOL1 variant rs73885319 and small vessel disease (lacunar) strokes among West Africans." (PMID 30471633, 2019). "Furthermore, APOL1 G2 homozygous individuals were shown to be at an increased risk for stroke compared to G1 two risk alleles." (PMID 26112018, 2015). "Given the recently reported association between APOL-1 variants and small vessel disease strokes among West Africans, there is justifiable scientific incentive to investigate the associations between CKD and stroke risk among indigenous Africans further." (PMID 30471633, 2019).
colorectal cancer (6 papers, 2016 to 2025). A primary or metastatic malignant neoplasm that affects the colon or rectum. "According to the research, vitexin can cause cell death by triggering apolipoprotein L1 (ApoL1)-mediated autophagy and JNK and suppresses the activity of heat shock factor 1 (HSF-1) to prevent the growth of colorectal cancer cells." (PMID 40725244, 2025). "For instance, the activation of apolipoprotein L1 (APOL1) is involved in HSF-1 mediated autophagic cell death in the treatment of colorectal carcinoma using Vitexin." (PMID 33027767, 2020). "Taken together, our study insights a probable novel association between HSF-1 and ApoL-1 was established in this study, which supports HSF-1 as a potential target of vitexin to improve treatment outcome in colorectal cancer." (PMID 29348836, 2017). "Several DEPs, such as APOE, APOA1, and APOL1, are known as representative HDL-associated molecules; however, they were excluded as biomarker candidates due to high fold changes observed in pancreatic or colorectal cancers." (PMID 33808296, 2021). "APOL gene overexpression, especially APOL1 and APOL6, has been reported to promote apoptosis in embryonic kidney cells, podocytes and colorectal cancer cell lines." (PMID 37924378, 2024). "To summarize, our study is the first to demonstrate that vitexin can effectively inhibit the proliferation of colorectal carcinoma cells by inhibiting HSF-1 activity, and lead to cell death by inducing autophagy mediated by JNK and ApoL1 activation." (PMID 29348836, 2017). "It has also been reported that overexpressed APOL1 G0 (without G1 or G2 allele) causes cell death in multiple human cell lines, DLD-1 (colorectal cancer), HepG2 (liver cancer), MCF-7 (breast cancer), and LNCaP, PC3, and DU145 (prostate cancer)." (PMID 27054572, 2016).
dyslipidemia (6 papers, 2019 to 2025). "This was in agreement with previous studies in which an association was found between APOL1 concentrations and plasma triglycerides and/or the metabolic syndrome." (PMID 37924378, 2024). "Whether APOL1 high-risk variants increase other diseases under dyslipidemia remains unclear and requires further investigation." (PMID 40459058, 2025). "However, whether APOL1 risk variants increase risk for extra-renal diseases in the setting of dyslipidemia remains unclear." (PMID 40459058, 2025). "We postulate that serum ApoL1 levels may elevate and exert certain biological activity in subjects with insulin resistance that frequently presents dyslipidemia marked by hypertriglyceridemia; however, the association between ApoL1 and insulin resistance has not been reported." (PMID 31619724, 2019). "We characterized a mouse model to investigate the role of APOL1 in dyslipidemia and cardiovascular diseases (CVDs)." (PMID 40459058, 2025). "We characterized a mouse model to investigate the role of APOL1 in dyslipidemia and cardiovascular diseases." (PMID 39803526, 2024). "The plasma levels of apoL1 have been reported to be increased in patients with metabolic syndrome, and an in vitro study has demonstrated that the insulin signaling pathway regulates both the synthesis and the secretion of apoL1 in hepatocytes." (PMID 35130909, 2022). "In T2DM, ApoL1 was higher in T2DM with metabolic syndrome, however ApoL1 was lower with β cell dysfunction." (PMID 31619724, 2019). "Non-diabetic subjects demonstrated triglyceride (standardized coefficients [s.c.] = 0.204, p < 0.05), body mass index (s.c. =0.232, p < 0.05) and HDL cholesterol (s.c. = −0.203, p < 0.05) as independent determinant of ApoL1 levels, and the significant elevation of ApoL1 in metabolic syndrome." (PMID 31619724, 2019). "We classified 126 facility volunteers into 3 groups, namely, non-obese, abdominally obese, and preliminary metabolic syndrome (pre-Mets)/Mets, and compared the ApoL1 levels between these groups." (PMID 31619724, 2019).
parasitic infections (6 papers, 2009 to 2025). "Mutations in apolipoprotein L1 (APOL1) are strongly associated with protection against parasitic infections and increased risk of kidney disease in individuals of African ancestry." (PMID 39975113, 2025). "Two variants of APOL1 (G1 and G2), provide resistance to parasitic infections in African Americans but are also implicated in kidney-related diseases and transplant outcomes in recipients." (PMID 38660426, 2024).
autoimmune disease (5 papers, 2011 to 2025). A disorder resulting from loss of function or tissue destruction of an organ or multiple organs, arising from humoral or cellular immune responses of the individual to their own tissue constituents. "Secondary etiologies were identified in 94 patients: HIV (13.8%), autoimmune disease (15.9%), and APOL1 high‐risk genotype (48.6%, 35/72)." (PMID 41397399, 2025). "Its pathogenesis is multifactorial and may be associated with infections, drugs, autoimmune diseases, and genetic factors, which include genetic susceptibility (APOL1 high-risk genotypes [APOL1-HRG]), or monogenic disorders." (PMID 41278320, 2025). "Exposures aimed at compensating for these metabolically compromised cellular states may improve the vascular consequences facing APOL1 variant carriers, and may be particularly important in those people with inflammatory, infectious, or autoimmune diseases." (PMID 36238153, 2022).
renal failure (5 papers, 2013 to 2024). "Studies from the US have shown that persons of African descent are also at increased risk for renal insufficiency and disease due to polymorphisms in the apolipoprotein L1 (APOL1) gene." (PMID 38540623, 2024).
schizophrenia (5 papers, 2006 to 2023). A major psychotic disorder characterized by abnormalities in the perception or expression of reality. "Single nucleotide polymorphisms and haplotypes in APOL1, 2 and 4, located on chromosome 22q12.3–13.1, are associated with schizophrenia in African-American, European-American, Chinese and Japanese populations." (PMID 38017264, 2023). "They conducted a family-based association study using 130 single nucleotide polymorphisms (SNPs) in APOL1-6 family members in 112 African-American, 114 European-American, 109 Chinese and 42 Japanese families with schizophrenia." (PMID 38017264, 2023). "Moreover, in humans, the ApoL1 gene is localized to chromosome 22q13.1, a region with loci suggested to be linked to susceptibility to schizophrenia." (PMID 31191249, 2019). "Another indication for the possible involvement of aberrant autophagy in schizophrenia relates to the apolipoprotein L1 (ApoL1) gene." (PMID 31191249, 2019). "Overexpression of ApoL1 induces autophagic cell death and expression of ApoL1 was found to be significantly upregulated in post-mortem brain of schizophrenia patients." (PMID 31191249, 2019). "This is reminiscent of the situation in the prefrontal cortex in schizophrenia, where expression of APOL1, 2 and 4 transcripts were increased, and myelin transcripts were decreased." (PMID 17205118, 2006). "The paralogous genes of GBP1, MT2A and APOL1, including GBP2, MT1G, MT1E, MT1F, MT1L and APOLD1, were also upregulated in the schizophrenia cases." (PMID 28809853, 2017).
AIDS (4 papers, 2019 to 2022). A syndrome resulting from the acquired deficiency of cellular immunity caused by the human immunodeficiency virus (HIV). "Our population genetic epidemiological data revealed a potential role of APOL1 variant alleles in protection against AIDS-related opportunistic infections." (PMID 33674766, 2021). "In this study, we assessed the influence of APOL1 variants on susceptibility to opportunistic infections in African Americans from four HIV/AIDS cohorts." (PMID 33674766, 2021). "In this study, we explored a possible influence of APOL1 variants on opportunistic infections in African Americans from four HIV/AIDS cohorts." (PMID 33674766, 2021). "Association between APOL1 G1-G2 variant alleles and incident clinical AIDS." (PMID 30733721, 2019). "To determine if the APOL1 association was due to a specific OI etiology, we used the LSOCA cohort, which enrolled only participants with an AIDS diagnosis." (PMID 33674766, 2021). "Little is known about the association of APOL1 genotypes with HIV viral load, HIV acquisition, or progression to AIDS." (PMID 30733721, 2019). "In the present study, we evaluate the genetic associations between APOL1 variants and HIV-1 acquisition, set-point viral load, and rate of progression to AIDS among African Americans enrolled in the ALIVE HIV-1 cohort." (PMID 30733721, 2019). "To assess the impact of APOL1 HR on disease progression in untreated individuals from date of seroconversion to CD4 <200 cell/mm3 and to incident AIDS, we performed time-to-event analysis for 227 African American seroincident participants." (PMID 30733721, 2019).
Hypercholesterolemia (4 papers, 2017 to 2025). An increased concentration of cholesterol in the blood. "In familial hypercholesterolemia, APOL1 serum levels are reduced and lower levels predict adverse cardiac events." (PMID 30998685, 2019).
hyperlipidemia (4 papers, 2022 to 2025). "The present study demonstrated a significant upregulation in several apolipoproteins, including APOC1, APOB, APOC4 and APOL1, but also in LCAT, suggesting a dysregulation in lipoprotein metabolism that could be partially related to the hyperlipidemia in IMN patients." (PMID 37511514, 2023).
hypertensive nephropathy (4 papers, 2022 to 2025). Kidney damage that results from chronically elevated blood pressure; complications include glomerular damage resulting in proteinuria and hematuria. "For example, the discovery of APOL1 risk polymorphisms may have an impact on kidney transplantation and hypertensive nephropathy therapy." (PMID 39728069, 2024). "Although there have been some genetic studies of hypertensive nephropathy, these studies have mainly focused on the apolipoprotein L1 (APOL1) gene." (PMID 35801212, 2022). "Strong associations (OR >10) were also observed between APOL1 high-risk genotypes and biopsy-confirmed FSGS, a clinical diagnosis of HIVAN/FSGS/hypertensive nephropathy, and biopsy-confirmed HIVAN (OR 30.16, 95% CI 12.48–72.88)." (PMID 35497797, 2022). "Understanding a patient’s APOL1 status may help to develop individualized therapy methods, perhaps leading to the better management of hypertensive nephropathy." (PMID 39728069, 2024).
fibrosis (3 papers, 2012 to 2025). the formation of excess fibrous connective tissue in an organ or tissue in a reparative or reactive process. "Ultimately, this study not only underscores the utility of the urine-derived immortalized UM30-OSN cell line, but also establishes its relevance as a valuable in vitro model for investigating APOL1-mediated kidney diseases such as fibrosis." (PMID 41225540, 2025).
HIV-1 infection (3 papers, 2016 to 2025). The type species of lentivirus and the etiologic agent of acquired immunodeficiency syndrome (AIDS). "We had 80% power to detect a potential association of APOL1 G1-G2 with HIV-1 infection, with an OR 1.35 for additive model and 1.93 for recessive model." (PMID 30733721, 2019). "This is not the case for those populations carrying the risk G1 and G2 polymorphic variants of APOL1 that, following HIV-1 infection, experience a much higher frequency of HIVAN development." (PMID 27599995, 2016). "APOL1 renal risk variants are most common in West Africa, where the prevalence of APOL1 HR genotypes approaches 25% but are also found throughout sub-Saharan Africa where HIV-1 infection is notably prevalent." (PMID 30733721, 2019). "People living with HIV-1 that carry two copies of the APOL1-RA have a ∼50% lifetime risk of developing HIVAN, and poorly controlled HIV-1 infection is the most powerful factor known to contribute to APOL1-associated kidney diseases." (PMID 40747773, 2025). "A recent in vitro study reported that APOL1 protein can inhibit HIV-1 infection of macrophage and monocytes by multiple mechanisms, including inhibition of transcription and degradation of HIV-1 Gag and Vif proteins." (PMID 30733721, 2019). "Our findings indicate that the presence of risk Vs of APOL1 is permissive of HIV-1 persistence in human podocytes in synergy with IL-1β, a cytokine that characterizes the inflammatory milieu of acute and chronic phases of HIV-1 infection." (PMID 27599995, 2016). "However, the mechanistic contribution of the APOL1 allelic state to kidney injury in HIV-1 infection remains to be elucidated." (PMID 27599995, 2016). "However, our genetic association study revealed no in vivo evidence of association of APOL1 renal risk alleles with HIV-1 infection acquisition or disease progression." (PMID 30733721, 2019).
Insulin resistance (3 papers, 2019 to 2022). Increased resistance towards insulin, that is, diminished effectiveness of insulin in reducing blood glucose levels. "In summary, the current observational study and in vitro examination demonstrated insulin resistance-mediated ApoL1 synthesis and secretion in the liver and alteration of ApoL1 distribution between lipoprotein fractions in Mets." (PMID 31619724, 2019). "A second major finding was the distinct expression and distribution pattern of ApoL1 in subjects with increased ApoL1 levels resulting from insulin resistance." (PMID 31619724, 2019). "The ApoL1 increase in T2DM3 is consistent with the results of this study because insulin resistance is the common basal pathophysiology of Mets and T2DM." (PMID 31619724, 2019). "Thus, the correlation between ApoL1 and clinical factors in this study is similar to that in the Japanese population with insulin resistance." (PMID 31619724, 2019). "We examined ApoL1 expression in 36 patients with T2DM characterized by insulin resistance." (PMID 31619724, 2019). "In agreement with previous findings, we found a significant and positive correlation between apoL1 and HOMA-IR as well as an inverse correlation with plasma adiponectin, reinforcing its potential role in insulin resistance." (PMID 35130909, 2022). "This observational study revealed several novel findings regarding insulin resistance-mediated ApoL1 biology in Mets and T2DM, including the elevation of serum ApoL1 in Mets." (PMID 31619724, 2019). "Lipoprotein fractionation analysis revealed the predominant distribution of ApoL1 in large HDL fraction, and the significant increase of ApoL1 in large LDL fraction in high ApoL1 samples with insulin resistance." (PMID 31619724, 2019).